FOXO1 (forkhead box O1)
Diseases named in the same sentence as FOXO1 in open-access papers (continued):
Sharing a sentence is not in itself a finding about the gene and the disease.
tumor (continued). "It responds to insulin, and its altered expression in tumor cells may allow both glucose uptake and phosphorylation of Akt and FOXO1 in adipocytes." (PMID 27551267, 2016). "Moreover, patients with a pJNK-positive (JNK active) and pFOXO1-postive (FOXO1 inactive) tumor had a higher survival rate than the remainder of the population (P = 0.004)." (PMID 27268017, 2016). "Despite mounting evidence of a tumor suppressive role for FOXO1, the mechanism by which FOXO1 activity is regulated remains unclear." (PMID 25909227, 2015). "Together, the results of the present study demonstrate that FOXO1 may function as a tumor suppressor in DLBCLs." (PMID 25909227, 2015). "We used in vivo electroporation in the mouse retina to ascertain if PIK3CA, AKT, and FOXO1 could substitute for PTEN loss in the control of RB/E2F-induced retinal apoptosis and tumor emergence." (PMID 25907958, 2015). "Recent studies suggest that FOXO1 is a tumor suppressor as well." (PMID 25984601, 2015). "FOXO1 is known as a tumor suppressor, and deregulation of FOXO1 is involved in a variety of tumors." (PMID 25888950, 2015). "In carcinogenesis, FOXO3 and FOXO1 both suppress tumor growth." (PMID 24864265, 2014). "Notably, the MSA-mediated inhibitory growth effect on ES tumors persisted beyond the treatment period and tumor growth delay was accompanied by increased FOXO1 protein levels, suggesting a potent anti-tumorigenic activity of MSA." (PMID 23995784, 2014). "Interestingly, U29415 tumor cells of Pax7CreER satellite cell lineage showed a paradoxical increase in mRNA levels of Pax7 and Pax3:Foxo1 when treated with 20 μM 5-Aza-2′deoxycytidine, 15 μM entinostat, and 5 μM SAHA." (PMID 25030697, 2014). "It has been established that FOXO1 functions as a tumor suppressor." (PMID 24886245, 2014). "Altogether, these data suggest that the observed differences in Pax3:Foxo1 mRNA levels could be explained by a different chromatin state in these loci depending on the tumor lineage of origin." (PMID 25030697, 2014). "Moreover, consistent with previous studies, the regulation of FOXO1 by specific miRNAs is essential in tumor development and progression." (PMID 25472505, 2014). "Expression of FOXO1 was analysed in normal and in tumor areas determined for each patient." (PMID 24260486, 2013). "Recent studies also suggested that FOXO1 is a tumor suppressor." (PMID 23615471, 2013). "FOXO1 expression was restricted to epithelial cells with a predominant localization in the nucleus in normal tissue and a shift to a cytoplasmatic localization in the tumor cells." (PMID 24260486, 2013). "The tumor suppressor function of FOXO1 can also be inhibited by protein kinase pathways." (PMID 23029264, 2012). "FoxM1 is expressed in glioma and pancreatic cancer cells and promotes angiogenesis by regulating VEGF expression, FoxO1/3/4 act as tumor suppressors in prostate cancer and leukemia, and recent evidence suggests that FoxC2 is a key factor in tumor development and disease progression." (PMID 22174714, 2012). "The atrophic effect of the tumor was also illustrated by a large increase in the expression of the Atrogin-1 and MurF1 atrogenes, and a significant increase in the expression of the Foxo1 and Foxo3 transcription factors, which are positive regulators of atrogene expression." (PMID 22257771, 2012). "To explore the possible mechanisms, we studied whether resveratrol played a role in the expression of the tumor suppressor genes by analysis of FoxO1 gene expression." (PMID 22532866, 2012). "Also, deletion of all FOXO1, FOXO3, and FOXO4 alleles in adult mice induced a cancer prone phenotype, supporting a tumour suppressing function of these proteins." (PMID 22848740, 2012).
tumor (continued). "Although it has been previously reported that FOXO1 in endothelial cells has an anti-angiogenic function, the correlation between FOXO1 and tumor angiogenesis remains unknown." (PMID 21696576, 2011). "Finally, resveratrol-treated mice showed significant inhibition in tumor growth which was associated with reduced phosphorylation of ERK, PI3K, AKT, FOXO1 and FOXO3a, and induction of apoptosis and FOXO target genes." (PMID 21980390, 2011). "Finally, resveratrol-treated mice showed significant inhibition in tumor growth which was associated with reduced phosphorylation of ERK, PI3K, AKT, FOXO1 and FOXO3a, and induction of apoptosis and FOXO target genes in tumor tissues." (PMID 21980390, 2011). "Furthermore, phosphorylation of PI3K/AKT activates FoxO1, a protein crucial for tumor suppression." (PMID 40820992, 2025). "Notably, FoxO1 plays a crucial role in maintaining CD8+ T cells-mediated tumor immunosurveillance." (PMID 40301310, 2025). "Therefore, we propose that compound I-27 may induce apoptosis in TNBC tumor cells via the PI3K/AKT/FoxO1 signaling pathway." (PMID 40820992, 2025). "Knockdown of FOXO1 accelerated ROS accumulation and led to significantly higher levels of ROS compared to the control, while FOXO1overexpression significantly reduced ROS levels, suggesting that FOXO1 could affect ROS levels in tumor cells." (PMID 41124013, 2025). "In addition, it remains unclear how FOXO1 maintains ROS homeostasis while regulating tumor cell proliferation at high ROS levels." (PMID 41124013, 2025). "In reverse experiments, CRISPR–Cas9-mediated targeting of FOXO1 in human Lewis Y (LeY) CAR T cells led to a loss of CD62L expression and a reduction in CAR T cell expansion upon extended culture, and impaired production of IFNγ upon co-culture with tumour cells." (PMID 38600376, 2024). "Given our previous observations of improved mitochondrial fitness in mouse FOXO1-ADA-overexpressing CAR T cells, we assessed the effect of wild-type FOXO1 overexpression on genes associated with metabolic pathways both before and after overnight co-culture with MCF7 tumour cells." (PMID 38600376, 2024). "Consequently, the HOXB2 inactivation or FOXO1 activation may be potential strategies to inhibit tumor progression and overcome radioresistance in NPC." (PMID 38617001, 2024). "Therefore, FoxO1 may restrict ME cell overgrowth and subsequently induce cell differentiation during the development stage or in the tumor environments." (PMID 38212454, 2024). "Interestingly, FOXO1(+) tumor‐induced M2 macrophages promoted tumor proliferation through the FAK–PI3K–AKT pathway and could be impeded by the PI3K inhibitor." (PMID 38296798, 2024). "Similarly, FOXO1 has a paradoxical impact on tumour immunity." (PMID 38899748, 2024). "Deletion of Foxo1 fails to rescue the loss of Rictor’s tumor inhibition effects in c-MYC HCC." (PMID 39325536, 2024). "We found that Zn intake could not increase tumor burden in FOXO1-deficient mice, and thus, we confirmed that FOXO1 plays a major role in Zn-mediated Treg cell differentiation and function." (PMID 39247196, 2024). "Similarly to the case of an inverse correlation between oncogenic EZH2 and tumor-suppressive RORα in breast cancer, we speculate that the potential oncogenic function of G9a might be augmented by the degradation of FOXO1, which is a known tumor suppressor." (PMID 36639369, 2023). "LINC00472 may be a potential tumor suppressor in OS by interacting with miR-300 and FOXO1." (PMID 37582104, 2023).
tumor (continued). "Strikingly and in contrast with FOXO3, which displayed tumour suppressor activity (p = 0.0069), FOXO1 was ranked second (p = 2.41 × 10−8) in the list of essential genes, a finding consistent with previous observations that inhibition or knock-down of FOXO1 negatively affects B-ALL growth." (PMID 36670235, 2023). "Moreover, FOXO1 could significantly promote tumor invasiveness, migration, and proliferation in OV cell lines, which was assessed through the Transwell, wound-healing, and CCK-8 assay, respectively." (PMID 37120633, 2023). "Similarly, another study has shown that the anti-tumor features of herbal medicine named Xihuang Pill are exerted through dephosphorylation of Akt and mTOR, resulting in decreased phosphorylation of FOXO1 and its subsequent translocation to the nucleus to induce apoptosis." (PMID 37821870, 2023). "Moreover, MEN1 increases the stability of the transcription factor FOXO1, which might promote or repress tumor growth in a dose-dependent manner." (PMID 38003662, 2023). "Furthermore, several studies have demonstrated the tumor suppressive role of FoxO1 in HCC." (PMID 37099251, 2023). "Moreover, restoring FOXO1 expression could be utilized in the sensitization of tumor cells to etoposide, BCNU, or cisplatin." (PMID 37821870, 2023). "Finally, the atrophy and metabolism associated protein (inactive) p-FOXO1 was downregulated in SED + T group compared to SED + NT group, indicating tumor-bearing may cause cardiac metabolism abnormalities and atrophy." (PMID 36531941, 2022). "Therefore, it has been controversial whether FOXO1 gene plays a role in tumor inhibition or promotion." (PMID 36290822, 2022). "Finally, we sought to investigate whether the anti-tumor effect of CDM in vivo was correlated with the regulation of the HDAC3/FOXO1 axis." (PMID 35126526, 2022). "Furthermore, the fact that the agents modulate FoxO1 activity through different molecular mechanisms increases the likelihood that these agents could cooperate to trigger robust tumor regression." (PMID 33772986, 2022). "Besides that, FOXO1 has been shown to function as a tumor inhibitor in many cancers, including GC." (PMID 34035814, 2021). "Finally, we demonstrated that several up-regulated transcription factors can activate several oncogenic miRNAs to inhibit tumor-suppressing transcription factors FOXO1 to down-regulate a certain number of tumor-suppressing miRNAs, which leaded to the occurrence and development of HCC." (PMID 34307154, 2021). "In tumor tissues, four protective genes (JAK2, IL2RG, EEF1E1, and UBB) showed relatively low expression in the high‐risk group; in contrast, the expression of four risk genes (EPS8, FOXO1, STAT5A, and PAPPA) was more highly in the high‐risk group than that in the low‐risk group." (PMID 34825509, 2021). "Cultures of these cells established in NB medium supplemented with B27 and bFGF revealed to contain only tumor cells as determined by DNA fluorescent in-situ hybridization using probes detecting the FOXO1 translocation (50 out of 50 cells positive for two copies of rearranged FOXO1)." (PMID 32934208, 2020). "Moreover, the ability of FOXO1-knockdown tumor cells to induce M2 polarization was impaired." (PMID 33052231, 2020). "In addition, the qRT-PCR revealed overexpression of CD68 in FOXO1(+) tumor tissues, suggesting that tumor-derived FOXO1 could promote macrophage infiltration in vivo." (PMID 33052231, 2020).
tumor (continued). "In addition, FOXO1 immunoreactivity was positively correlated with poor tumor grade (p = 0.004)." (PMID 31823759, 2019). "Given that HDAC inhibitors increase FOXO1 expression, thereby inhibiting tumor growth, and that silencing FOXO1 dampens this effect, we are tempted to speculate that autophagy and lysosomal biogenesis activated by MiT/TFE and/or FOXH1 may be the pathways of choice for targeted cancer therapy." (PMID 31399583, 2019). "Interestingly, this tumor showed copy number oscillation compatible with chromothripsis on chromosomes 13, on which FOXO1 and STK24 are located, strongly suggesting that this may be the mechanism underlying the gene fusion." (PMID 30514397, 2018). "Thus, it can be speculated that the evaluation of FOXO1 and pSerine256-FOXO1 in tumor biopsies might be of clinical relevance in patients with EACs." (PMID 30478420, 2018). "As FOXO1 connects to several of the cancer-associated genes adjacent to PBX3 (though not to PBX3 directly), the relative prominence of both FOXO1 and AKT1 might reflect a potential tumor-inhibiting effect in combination with PBX3 and its neighbors." (PMID 28957313, 2017). "Thus, the Pax7CreER postnatal satellite cell lineage did not appear to be poised for giving rise to aRMS when the Pax3:Foxo1 oncogene at the Pax3 locus is triggered; instead, cells of Pax7CreER satellite cell lineage had a tendency to give a spindle cell-like tumor phenotype." (PMID 25030697, 2014). "Therefore, repression of MYC and BCL2L1 might contribute to the tumor suppressor effects of FOXO1 in PMBL." (PMID 24977668, 2014). "Therefore, FOXO1 is considered to be as a putative tumor suppressor, and better understanding of the mechanisms that regulate FOXO1 activity may provide clues of novel targets for therapeutic intervention." (PMID 24886245, 2014). "Therefore, decline of phosphorylation of FOXO1 and FOXO3a caused by CAPE treatment will elevate their tumor suppressor activity, which may contribute to the growth inhibition of TW2.6 cells." (PMID 23615471, 2013). "The results presented in this study indicate that FOXO1 has a tumor suppressor function, while FADD has a tumor-promoting function in OS following anticancer drug treatment." (PMID 41596582, 2026). "FoxO1 positively regulates MHC-II gene expression, and its absence in TAMs leads to decreased MHC-II levels, further promoting tumor growth." (PMID 40764998, 2025). "Meanwhile, the upregulated G6PD expression by FOXO1 can promote PPP progression and further enhance the growth of tumor cells in vivo and in vitro." (PMID 41124013, 2025). "PAX3::FOXO1 activity was augmented by MYCN overexpression, and xenografting these cells resulted in a faster tumor growth rate than PAX3::FOXO1 alone." (PMID 40599857, 2025). "Throughout tumor sections from mice treated with VDC597, intranuclear FOXO1 immunolabeling was increased compared with specimens from the control group." (PMID 41106249, 2025). "Tumor models were generated and treated with Sora, Sora combined with an anti-CD25 antibody, or Sora combined with the Foxo1 inhibitor AS1842856." (PMID 39743020, 2025). "The FOXO (Forkhead box O) transcription factors—mainly FOXO1, FOXO3a, FOXO4, and FOXO6—are key tumor suppressors in many cancers." (PMID 41300302, 2025). "Compared with controls, IHC of FFPE tumor sections from mice treated with VDC597 exhibited reduced immunoreactivity for pAKT, p4EBP1, and Ki67, as well as increased intranuclear FOXO1 immunolocalization." (PMID 41106249, 2025).
tumor (continued). "In other studies, it has also been shown that the activation of the ERK/MAPK signaling pathway can lead to the activation of the transcription factors FOXO1 and FOXO3, which also function as tumor suppressors." (PMID 41462911, 2025). "Clinically, the low expression of GnRHR or FOXO1 and high expression of AKT correlate with tumor aggressiveness and unfavorable clinical outcomes, suggesting their utility as novel prognostic biomarkers in EOC patients." (PMID 41458598, 2025). "The specific mechanism is that FOXO1 transcriptionally activates G6PD to enhance the antioxidative capacity and, consequently, the anti-apoptotic and proliferative abilities of tumor cells in response to oxidative stress." (PMID 41124013, 2025). "WT, Foxo1-AAA, or Stat4Y693A KP.SIY lung tumor-bearing mice were treated with MSA-IL2 and MSA-IL12 (alone or in combination) on day 7 of tumor growth and monitored daily for survival." (PMID 41203628, 2025). "ERK can also influence FOXO1 and FOXO3 transcription factors, which control the expression of several tumor suppressor genes." (PMID 41462911, 2025). "RT-PCR analysis of tumor tissues showed that CUDC-907, both alone and with MPA, effectively increased mRNA expression of PR and its downstream target FOXO1 in most samples." (PMID 41262902, 2025). "Transcriptomic analysis and in vivo mouse experiments confirmed that compound I-27 inhibits tumor angiogenesis and induces TNBC cell apoptosis via the ID1/TSP-1 and PI3K/AKT/FoxO1 signaling pathways." (PMID 40820992, 2025). "In a follow-up study, PAX3::FOXO1 genetically cooperates with transcriptional target, FGF8 (with constitutive MYCN expression), to enhance cell proliferation and tumor growth." (PMID 40599857, 2025). "FOXO1, a downstream target gene of AKT, plays a crucial role in regulating various aspects of tumour cell proliferation, the cell cycle, DNA damage repair, and glucose metabolism." (PMID 41331197, 2025). "Using this PAX3::FOXO1 zebrafish tumor model, this group also identified a novel PAX3::FOXO1 target gene her3, the human ortholog HES3, that is upregulated in fusion positive RMS patients." (PMID 40599857, 2025). "The inhibition of FOXO1 in CAR T cells, furthermore resulted in a more exhausted phenotype and weakened anti-tumor response, whereas overexpression of FOXO1 enhanced anti-tumor immunity, increased mitochondrial mass, and induced stemness." (PMID 41346587, 2025). "MTDH promotes tumor proliferation by inhibiting transcriptional factor FOXO1 and activating MEK/ERK and NFκB1 pathways, thereby driving tumor progression." (PMID 40149331, 2025). "Taken together, these results suggest that GnRHR, FOXO1 and AKT are potentially dynamic regulators of tumor behavior and potentially represent promising therapeutic targets and prognostic indicators for EOC." (PMID 41458598, 2025). "Phosphorylation of the Forkhead Box O1 (FOXO1) and O3 (FOXO3) transcription factors at positions T24 and T23, respectively, renders these proteins to act as tumor suppressors and play a role in regulating fibrosis." (PMID 41373844, 2025). "Tumor tissues of the CK treatment group showed inhibited GPX4 and SLC7A11 expression and down-regulated p-FOXO1." (PMID 38664638, 2024). "Both genetic and pharmacological inhibition of FOXO1 in CAR T cells results in a more exhausted phenotype and weakened anti-tumor responses, while overexpression of FOXO1 enhances anti-tumor immunity, increases mitochondrial mass and induces more stemness." (PMID 38987856, 2024). "In terms of SIRT1’s oncogenic role, inhibiting it can disrupt tumorigenesis; for instance, LITAF increases FOXO1 levels, leading to SIRT1 downregulation, which diminishes the stemness and malignant phenotype of tumor cells." (PMID 39403142, 2024). "ARMS is characterised by the presence of a PAX 3: or less commonly PAX 7:FOXO1 gene fusion, which is present in around 80% of ARMS tumours." (PMID 38473359, 2024).